FGL1 (fibrinogen like 1)
Diseases named in the same sentence as FGL1 in open-access papers (continued):
Sharing a sentence is not in itself a finding about the gene and the disease.
tumor (continued). "On day 13 after MC38 challenge, a significant reduction in tumor nodules and maximum tumor volumes in the liver was observed in anti-FGL1 mAb–treated mice compared with control IgG–treated mice." (PMID 38973608, 2024). "Subsequent analysis using the CancerSCEM database, revealed high expression of FGL1 in malignant tumor cells and low expression of FGL1 in other cell types." (PMID 39085849, 2024). "As the proportion of FGL1+CTCs decreased, the patient showed a PR in tumor assessment (PFS = 10.3 months)." (PMID 39085849, 2024). "Subsequently, the proportion of FGL1+ CTCs increased, resulting in a tumor assessment of PD (PFS = 6.8 months)." (PMID 39085849, 2024). "Previous research has shown that FGL1 induces the generation of regulatory T cells and promotes the formation of an immunosuppressive tumor microenvironment through interactions with various immune cells." (PMID 38702629, 2024). "Another newly discovered LAG-3 functional ligand, FGL1, is a member of the liver-secreted fibrinogen family of proteins and is highly expressed in a variety of tumor cells, such as melanoma, lung cancer, and colorectal cancer cells." (PMID 38177102, 2024). "HCC patients with higher levels of FGL1 on circulating tumor cells showed a higher proportion of advanced tumor node and metastasis stage as well as distant metastases and worse postoperative survival." (PMID 38973608, 2024). "The results revealed that inhibition of FGL1 expression partly attenuated the effects of Stat3 overexpression on tumor cell proliferation, migration, and invasion." (PMID 39085849, 2024). "Using different animal models and clinical tumor specimens, we demonstrated that FGL1 is highly expressed in liver metastases of gastrointestinal tumors and boosts tumor growth by inhibiting T-cell function." (PMID 37872170, 2023). "We constructed a Hepa1-6 mouse tumor cell line using lentivirus transfection and verified that shRNA-mediated Fgl1 knockdown was effective using WB." (PMID 36993960, 2023). "Consistently, half-life analysis using cycloheximide pulse-chase analysis showed that downregulation of OTUD1 attenuated the protein half-life of FGL1 in tumor cells cultured with TAM-CM." (PMID 37872170, 2023). "Taken together, these data suggest that FGL1 promotes metastatic tumor growth by reducing tumor-infiltrating T cells in the liver microenvironment." (PMID 37872170, 2023). "Overall, this study uncovers the critical roles and posttranslational regulatory mechanism of FGL1 in promoting metastatic tumor progression, highlighting the TAM-OTUD1-FGL1 axis as a potential target for cancer immunotherapy." (PMID 37872170, 2023). "LAG3 was the most promising immune checkpoint after PD-1 and CTLA-4, and higher LAG3 and FGL1 expression promoted tumor growth by suppressing the immune microenvironment." (PMID 36843949, 2023). "Benzethonium chloride, an FDA-approved antiseptics, curbs FGL1 secretion, thereby inhibiting liver metastatic tumor growth." (PMID 37872170, 2023). "The results show that FGL1 expression levels were upregulated in tumor tissue and were also significantly increased in liver metastatic tissues compared with paired primary tissues in CRC and GC, analyzed using a tissue microarray (SYSUCC)." (PMID 37872170, 2023). "In the neoadjuvant anti-PD-1 plus chemotherapy GC cohort, higher plasma FGL1 levels indicated a worse clinical stage of the tumor." (PMID 37872170, 2023). "Another functional ligand for LAG-3 is the fibrinogen-like protein 1 (FGL1), secreted by the liver and human tumor cells." (PMID 38162657, 2023). "Tumor cells overexpress FGL1 and PD-L1, which, respectively, bind to LAG-3 and PD-1 on T cells, forming important signaling pathways (FGL1/LAG-3 and PD-1/PD-L1) that negatively regulate immune responses." (PMID 37509610, 2023). "In our data, accumulated TAMs in the liver microenvironment enhanced the stabilization of the immunosuppressive molecule FGL1 and promoted metastatic tumor progression." (PMID 37872170, 2023).
tumor (continued). "In fact, FGL-1 expression in circulating tumor cells has been related to a poor prognosis in patients with HCC who underwent resection." (PMID 37941812, 2023). "FGL1, fibrinogen-like protein 1, which is known as a novel potential immune checkpoint target, was recognized to be upregulated in tumor tissues and plasma specimens of ccRCC patients, and high FGL1 expression predicted a poor prognosis." (PMID 35299868, 2022). "It is worth noting that when the interaction between LAG3 and ligand FGL1 is blocked by monoclonal antibodies, the T cell response in the tumor is enhanced and the tumor volume decreases, which provides a new idea for targeted immunotherapy." (PMID 35590394, 2022). "It is possible that the engagement of LAG-3 by FGL1 in the tumour micro-environment prevents an effective anti-cancer immune response." (PMID 35265944, 2022). "Models show that FGL-1 inhibits the antigen-specific activation of CD8+ T-cells and the blockade of FGL-1/LAG-3 interaction stimulates tumor immunity." (PMID 36140182, 2022). "The emergence of FGL1 as a major functional ligand of LAG3 has attracted great attention in the field of tumor immunotherapy." (PMID 34975333, 2022). "In order to further explore the FGL1 expression level of different types of circulating tumor cells, we assign a value to the FGL1 expression level of each CTC." (PMID 35273912, 2022). "The result showed that the expression of FGL1 in various malignant tumors were different in tumor tissues from normal tissues." (PMID 35273912, 2022). "In the present study, bioinformatics analysis was first used to probe the expression profile of FGL1 in multiple malignant tumor tissues and paired normal tissues, and to explore the possible relationship between FGL1 and prognosis of HCC patients." (PMID 35776395, 2022). "High LAG-3 and FGL1 expression boosts tumor growth by inhibiting the immune microenvironment, essentially helping the tumor cells to evade autoimmune elimination." (PMID 35885017, 2022). "Hepatocytes generally release FGL1 in the liver, but tumor cells can also express large amounts of FGL1, corresponding to poor patient prognosis and immunotherapy resistance." (PMID 35999569, 2022). "Bioinformatic results showed that FGL1 expression was abnormal in various tumor and it was correlated with the infiltration level of several immune cells." (PMID 35273912, 2022). "The differential expression analysis result showed that FGL1 expression level in tumor tissue compared to normal tissue was various among several tumors." (PMID 35273912, 2022). "This article detected the expression of FGL1 in circulating tumor cells of HCC patients and found that its expression was related to the poor prognosis." (PMID 35273912, 2022). "The present study employs bioinformatics analysis to probe the expression profile of FGL1 in multiple malignant tumor tissues and paired normal tissues, and to explore the possible relationship between FGL1 and HCC prognosis." (PMID 35776395, 2022). "FGL1 was detected in the circulating tumor cells of 10(83.3%) of them, and 8 of these 10 patients did not respond to immunotherapy." (PMID 35273912, 2022). "Targeting FGL1 therapy or combined with PD-1/PD-L1 antibodies can enhance the effect of anti-tumor therapy." (PMID 35273912, 2022). "Targeting FGL1 is advantageous as it targets the tumor cells and exploit its effect on immune cells, making it a superior selective therapeutic strategy." (PMID 35885017, 2022). "Expectedly, the expression of FGL1 in the liver hepatocellular carcinoma (LIHC) was higher than in any other malignant tumor tissues, and lower than in normal liver tissues." (PMID 35776395, 2022). "As a novel functional ligand of lymphocyte-activation gene 3 (LAG3), FGL1 can promote the proliferation of tumor cells." (PMID 34975333, 2022). "Numerous studies had reported that FGL1 knockdown either inhibits or promotes tumor cell proliferation." (PMID 34956878, 2021).
tumor (continued). "Apart from mediating the EMT process, FGL1 is also involved in tumor proliferation, apoptosis, radiation and drug sensitivity." (PMID 34526102, 2021). "HLA-II over-expression by tumor cells and fibrinogen-like 1 (FGL1), a protein secreted by liver cells and tumor cells, are ligands of LAG-3, and their secretion impact the expression of LAG-3 in T cells, promoting an immunosuppressive function." (PMID 34447383, 2021). "Infiltration of myeloid-derived CD11b+ and Ly6G+ immune cells in tumor microenvironment (TME) was strikingly decreased when FGL1 expression reduced." (PMID 34956878, 2021). "Western blotting and IHC were used to examine the expression of FGL1 protein in specimens of ccRCC tumor and adjacent normal tissues." (PMID 34956878, 2021). "So, knocking down FGL1 can help to repress neutrophil accumulation in tumor by reducing neutrophils transmigration through blood vessels." (PMID 34956878, 2021). "Based on these observations, our study showed that FGL1 achieves its function by influencing the release of cytokines and chemokines from cancer cells, which can dampen anti-tumor immune responses in TME." (PMID 34956878, 2021). "Third, although there are no reports of anti-FGL1 mAbs undergoing clinical trials, the proven anti-tumor effect of FGL1 block indicates the enormous potential of developing anti-FGL1 mAbs." (PMID 35111155, 2021). "Depletion of FGL1 significantly inhibited tumor growth and lung metastasis in orthotopic xenograft mouse model." (PMID 34956878, 2021). "Our results demonstrated that FGL1 knockdown significantly decreased the infiltrated number of myeloid-derived CD11b+ cells and ly6G+ cells in primary tumor tissues." (PMID 34956878, 2021). "Galectin-3 (Gal-3), liver sinusoidal endothelial cell lectin (LSECtin) and fibrinogen-like protein 1 (FGL1) are LAG-3 ligands that are frequently expressed in the tumor environment." (PMID 34575943, 2021). "Targeting FGL1 acts on both tumor cells themselves and immune cells, which exerts a two-way synergistic effect on advanced cancers through a targeted therapeutic strategy." (PMID 34526102, 2021). "We present a comprehensive overview of the role of LAG3/FGL1 in cancer, suggesting novel anti-tumor therapy strategies." (PMID 35111155, 2021). "In other words, blocking the FGL1-LAG-3 interaction with monoclonal antibodies stimulates tumor immunity and promotes a killing effect on tumors." (PMID 33832428, 2021). "FGL1 is produced in excess by tumor cells, and the plasma concentration of FGL1 is negatively correlated with the prognosis and resistance to the PD-1/PD-L1 axis blockade." (PMID 33632231, 2021). "Collectively, these findings provided insights into the functions of FGL1 in tumor progression, suggesting that targeting FGL1 can be a potential therapeutic strategy for ccRCC." (PMID 34956878, 2021). "As tumor EMT is tightly associated with prognosis and drug resistance, the specific mechanism by which FGL1 regulates tumor EMT needs to be clarified." (PMID 34526102, 2021). "Accordingly, depending on the cell type and origin of the cancer, FGL1 can be upregulated or downregulated acting as an oncogene or tumor suppressor, thus indicating the complexity and diversity of roles played by FGL1 in different cancers." (PMID 34956878, 2021). "Among these survival-related genes, FGL1 and ANKDD1A were intriguingly closely associated with the tumor microenvironment and immune infiltration." (PMID 33832428, 2021). "Immunohistochemistry of the tumor tissues revealed that knockdown of FGL1 alone or co-culture with gefitinib significantly decreased the Ki-67 levels (P < 0.05)." (PMID 32778129, 2020). "It was found that the anti-tumor effect of anti-FGL1 monoclonal antibody depended on LAG-3 and anti-LAG-3 depended on FGL1 rather than MHC-II or other ligands." (PMID 33344447, 2020).
tumor (continued). "To clarify the potential mechanisms by which FGL1 mediates gefitinib acquired resistance, we measured the expression of proteins related to apoptosis and proliferation in tumor cells by western blot analysis." (PMID 32778129, 2020). "FGL1 shows high expression on human cancer cells, and inhibits the antigen-specific T cell response, while blockade of the LAG-3–FGL1 interaction using antibodies enhanced its anti-tumor effects." (PMID 32714324, 2020). "FGL1 can be overexpressed on tumor cells and blocking of FGL1-LAG-3 interactions led to an increased immune activity." (PMID 32133304, 2020). "As expected, we observed an increase in the levels of markers that are important for immune responses and inflammation (Saa1, Saa2, Lcn-2, Ltf, and Orosomucoid-2) and initiating and promoting tumor growth (Ighg1, Scube3, and Fgl1)." (PMID 33110211, 2020). "Mouse xenograft experiments showed that FGL1 knockdown in PC9/GR tumor cells enhanced the inhibitory and apoptosis-inducing actions of gefitinib." (PMID 32778129, 2020). "The recent study has also demonstrated that the anti-tumor effects of anti-FGL1 or anti-LAG-3 mAb are depending on CD8+ T cells." (PMID 32762721, 2020). "Flow-cytometric analysis of cells isolated from freshly isolated tumor tissues revealed that both FGL1 knockdown alone and FGL1 knockdown plus with gefitinib significantly increased the apoptotic rate (P < 0.05)." (PMID 32778129, 2020). "Collectively, these results suggested that FGL1 knockdown suppresses tumor growth and significantly enhances the antitumor effect of gefitinib in vivo." (PMID 32778129, 2020). "Blocking the FGL1-LAG-3 pathway has been shown to enhance the anti-tumor activity of CD8+ T cells." (PMID 40356928, 2025). "Collectively, FGL1 may have an independent role in promoting tumor metastasis in addition to its currently known immunosuppressive effect." (PMID 41024301, 2025). "Downregulation of FGL1 inhibited lymph tube formation and, ultimately, tumor lymph node metastasis." (PMID 41024301, 2025). "Interestingly, the FGL1 gene is located on chromosome 8 both in humans and mice in a region containing several tumor suppressor genes such as VPS37A or DLC1." (PMID 40832769, 2025). "shFGL1_AAV9 was constructed for FGL1 knockdown to inhibit tumor proliferation in vivo." (PMID 41024301, 2025). "FGL1 plays a regulatory role in tumor glycolysis through the PI3K/AKT/HIF-1α pathway." (PMID 41024301, 2025). "This dual role of immunomodulation and intrinsic tumor suppression makes LAG3 distinct from PD‐1/CTLA‐4 and may explain the association of anti‐PD‐1 resistance with LAG3/FGL1 co‐expression." (PMID 41025546, 2025). "FGL1 promotes metastatic tumour progression via mediating immune escape." (PMID 39778025, 2025). "Downregulation of FGL1 inhibited tumor proliferation in vivo." (PMID 41024301, 2025). "Notably, FGL1 knockdown in situ significantly inhibited tumor metastasis and improved survival rates (P = 0.0751)." (PMID 41024301, 2025). "Additionally, the therapeutic effect of anti-FGL1 mAb i.p. once every 3 days 5 times was demonstrated by the significantly prolonged survival of mice with liver metastasis of B16-F10 tumor cells." (PMID 38973608, 2024). "In addition to MHC-II, LAG-3 also binds to other ligands, such as liver sinusoidal endothelial cell lectin (LSECtin), Galectin-3 (Gal-3), and fibrinogen-like protein 1 (FGL1), which further inhibit T cell function and promote tumor immune evasion." (PMID 39743998, 2024). "Furthermore, by using an established CRC liver metastasis model of MC38 tumor cells, we explored the therapeutic effect of the anti-FGL1 mAb i.p. once every 4 days 4 times." (PMID 38973608, 2024).
tumor (continued). "In the liver orthotopic tumor of Hepa1-6 in situ inoculation, the morphology of liver showed that pretreatment with the anti-FGL1 mAb inhibited orthotopic tumor growth, which was further verified by the significantly decreased tumor diameter in the livers of the anti-FGL1 mAb–treated mice." (PMID 38973608, 2024). "We identified 9 genes whose increased expression was significantly associated with tumor size in female LC patients of which four code for MAPK signaling molecules (DUSP4, FGL1, TXNRD1, PLA2G4E), three for oncogenes (KRT16, STRIP2 and TNS4), tumor suppressor cystatin 5, and NQO1." (PMID 38245882, 2024). "The interaction between the FGL-1 in the cytoplasm of tumor cells interacts with LAG-3 on the surface of various lymphocyte cells and whether other molecular signals are involved in this process remain to be determined." (PMID 39252941, 2024). "This suggests that FGL-1 plays a prominent role in tumor growth and invasion." (PMID 39331884, 2024). "Importantly, the expression of FGL1 was confirmed on lung adenocarcinoma cells which indicates another mechanism of tumor-mediated immune cell suppression." (PMID 38384472, 2024). "Therefore, FGL1 facilitated NSCLC progression by augmenting tumor cell proliferation and metastasis." (PMID 39085849, 2024). "In addition to these advancements, our study has explored the clinical translational potential of FGL1 using a novel circulating tumor cells (CTCs) platform." (PMID 39085849, 2024). "The independent ligands with which LAG-3 interacts are Major Histocompatibility Complex II (MHC-II), Liver and lymph node sinusoidal endothelial cell C-type lectin (LSECtin), and fibrinogen-like protein 1 (FGL1) localized on antigen-presenting cells and tumor cells." (PMID 38893211, 2024). "High plasma FGL1 levels are associated with poor outcomes in cancer patients undergoing anti-PD1 therapy, suggesting that it might contribute to tumor resistance." (PMID 38556085, 2024). "Blocking FGL1 has been shown to enhance T cell anti-tumor activity." (PMID 38816776, 2024). "On day 21 after challenge, the morphology of the liver showed that pretreatment with the anti-FGL1 mAb inhibited liver metastasis of the MC38 tumor cells, which was further verified by the significantly decreased number of tumor nodules in the liver of the anti-FGL1 mAb–treated mice." (PMID 38973608, 2024). "Similarly, a significant reduction in tumor nodules in the liver was also observed in anti-FGL1 mAb–treated mice on day 21 after MC38 challenge." (PMID 38973608, 2024). "While FGL1 may behave as a tumor suppressor in HCC, Lin and authors have illuminated a role of FGL1 by highlighting its contribution to antitumor immunity in HCC." (PMID 37115694, 2023). "Notably, these results contrast with prior findings in which downregulation of FGL1 in HCC increases the rates of tumor formation, and is a positive prognosticator." (PMID 37115694, 2023). "However, the Fgl1-knockdown group showed a substantial reduction in tumor size, cancer nodules, and liver enzymes, as well as a longer survival time and more CD8+ TRM cells in HCC." (PMID 36993960, 2023). "The knockdown of Fgl1 in Hepa1-6 cells inhibited tumor growth." (PMID 36993960, 2023). "Mechanistically, tumor-associated macrophages (TAMs) activate NF-ĸB by secreting TNFα/IL-1β in the liver microenvironment and transcriptionally upregulate OTU deubiquitinase 1 (OTUD1) expression, which enhances FGL1 stability via deubiquitination." (PMID 37872170, 2023). "FGL1 plays a role in proliferation and metabolism and can be expressed by tumor cells." (PMID 37215135, 2023). "In addition, this study elucidates the critical roles and regulatory mechanisms of FGL1 in promoting metastatic tumor cell progression, emphasizing its prognostic value and the clinical significance of immunotherapy." (PMID 37872170, 2023).